ABCA7 (ATP binding cassette subfamily A member 7)
Description:
Catalyzes the translocation of specific phospholipids from the cytoplasmic to the extracellular/lumenal leaflet of membrane coupled to the hydrolysis of ATP. Transports preferentially phosphatidylserine over phosphatidylcholine. Plays a role in lipid homeostasis and macrophage-mediated phagocytosis. Binds APOA1 and may function in apolipoprotein-mediated phospholipid efflux from cells. May also mediate cholesterol efflux. May regulate cellular ceramide homeostasis during keratinocyte differentiation. Involved in lipid raft organization and CD1D localization on thymocytes and antigen-presenting cells, which plays an important role in natural killer T-cell development and activation (By similarity). Plays a role in phagocytosis of apoptotic cells by macrophages (By similarity). Macrophage phagocytosis is stimulated by APOA1 or APOA2, probably by stabilization of ABCA7 (By similarity). Also involved in phagocytic clearance of amyloid-beta by microglia cells and macrophages (By similarity). Further limits amyloid-beta production by playing a role in the regulation of amyloid-beta A4 precursor protein (APP) endocytosis and/or processing. Amyloid-beta is the main component of amyloid plaques found in the brains of Alzheimer patients.
Synonyms: ABCX; ABCA-SSN; AD9
Tractability: Small molecule: a structure with a bound ligand is known; it belongs to a druggable protein family. Antibody: UniProt places it where antibodies can reach, with high confidence; its Gene Ontology location is reachable by antibodies, with high confidence; UniProt predicts a signal peptide or a membrane-spanning region; the Human Protein Atlas places it where antibodies can reach. PROTAC: ubiquitination databases record sites on it.
Gene: Protein-coding gene on chromosome 19 (1,039,997 to 1,065,572, forward strand). Ensembl gene ENSG00000064687.
Subcellular location: Cell membrane; Golgi apparatus membrane; Early endosome membrane; Cytoplasm; Cell projection, ruffle membrane; Cell projection, phagocytic cup; Cytoplasm (Isoform 2); Endoplasmic reticulum
Subcellular location (Human Protein Atlas): Golgi apparatus; Plasma membrane; Cell Junctions
Pathways (Reactome):
Transport of small molecules: ABC transporters in lipid homeostasis
Gene Ontology:
Molecular function: apolipoprotein A-I receptor activity; ATPase-coupled intramembrane lipid transporter activity; floppase activity; phosphatidylcholine floppase activity; phosphatidylserine floppase activity; phospholipid transfer activity; protein binding; ATPase-coupled transmembrane transporter activity; ABC-type transporter activity; ATP binding; ATP hydrolysis activity
Biological process: amyloid-beta formation; apolipoprotein A-I-mediated signaling pathway; cholesterol efflux; high-density lipoprotein particle assembly; phospholipid efflux; phospholipid translocation; regulation of amyloid precursor protein catabolic process; amyloid-beta clearance by cellular catabolic process; lipid transport; memory; negative regulation of amyloid precursor protein biosynthetic process; negative regulation of amyloid-beta formation; negative regulation of endocytosis; negative regulation of MAPK cascade; negative regulation of PERK-mediated unfolded protein response; plasma membrane raft organization; positive regulation of amyloid-beta clearance; positive regulation of cholesterol efflux; positive regulation of engulfment of apoptotic cell; positive regulation of ERK1 and ERK2 cascade; positive regulation of phagocytosis; positive regulation of phospholipid efflux; positive regulation of protein localization to cell surface; protein localization to nucleus; regulation of lipid metabolic process; and 2 more
Cellular component: cell junction; cytoplasm; endoplasmic reticulum; Golgi apparatus; plasma membrane; cell surface; early endosome membrane; glial cell projection; Golgi membrane; phagocytic cup; ruffle membrane; membrane
Genetic constraint (gnomAD): Loss-of-function variants: 253 observed, 205.23 expected, observed/expected ratio (o/e) 1.23, 90% interval 1.11 to 1.37. The synonymous counts are far from expectation, so gnomAD's model fits this gene poorly and the ratio says little. Missense variants: 3,235 observed, 2,721.7 expected, observed/expected ratio (o/e) 1.19, 90% interval 1.15 to 1.22. Synonymous variants: 1,454 observed, 1,191 expected, observed/expected ratio (o/e) 1.22, 90% interval 1.17 to 1.27.
Homologues: Orthologues: macaque ABCA7 (94% identical), chimpanzee ABCA7 (84% identical), pig ABCA7 (82% identical), guinea pig ABCA7 (80% identical), dog ABCA7 (78% identical), rat Abca7 (78% identical), mouse Abca7 (78% identical), Caenorhabditis elegans abt-2 (27% identical), zebrafish abca7 (26% identical), Drosophila melanogaster Abca3 (25% identical), Caenorhabditis elegans abt-4 (24% identical), Drosophila melanogaster ldd (23% identical), and 8 more. Paralogues in human: ABCA1 (53% identical), ABCA4 (46% identical), ABCA2 (38% identical), ABCA12 (32% identical), ABCA13 (32% identical), ABCA3 (28% identical), ABCA9 (20% identical), ABCA8 (20% identical), ABCA5 (19% identical), ABCA6 (19% identical), ABCA10 (19% identical).
Diseases named in the same sentence as ABCA7 in open-access papers:
ABCA7 is named in the same sentence as 61 diseases in open-access papers, as found by Europe PMC text mining. Sharing a sentence is not in itself a finding about the gene and the disease. The quoted sentences say what the papers report.
Alzheimer disease (76 papers, 2011 to 2026). A progressive, neurodegenerative disease characterized by loss of function and death of nerve cells in several areas of the brain leading to loss of cognitive function such as memory and language. "ABCA7 protein is an ATP-binding cassette (ABC) lipid transporter linked to an increased risk of Alzheimer’s disease." (PMID 40724879, 2025). "Specific genetic variants in the ATP-binding cassette transporter A7 locus (ABCA7) are associated with an increased risk of Alzheimer’s disease (AD)." (PMID 39871385, 2025). "This meta-analysis aimed to evaluate the association of ABCA7 polymorphisms with AD risk, including specific subtypes such as late-onset Alzheimer’s disease (LOAD)." (PMID 39484364, 2024). "It is highly expressed in the brain, particularly in microglia, and loss-of-function mutations in ABCA7 are significantly associated with Alzheimer’s disease (AD), as demonstrated in genome-wide association studies (GWAS) across various populations." (PMID 39358554, 2024). "The roles of ABCA7 variants in sterol and lipid transport and metabolism makes them one of the top risk factors for Alzheimer’s disease development." (PMID 37242805, 2023). "Adenosine triphosphate-binding cassette transporter subfamily A member 7 (ABCA7) is a major risk factor for Alzheimer’s disease." (PMID 37681876, 2023). "The Alzheimer’s disease (AD) risk gene ABCA7 has suggested functions in lipid metabolism and the immune system." (PMID 37946268, 2023). "Our unbiased lipidomic study has demonstrated that deletion of the Abca7 gene causes lipid dysregulation that impacts on brain cellular processes associated with Alzheimer’s disease pathology in a sex-specific manner." (PMID 35620166, 2022). "Since loss of function mutations in the ABCA7 gene exhibit strong associations with late-onset Alzheimer’s disease across racial groups, we also studied the effects of ABCA7 deficiency in the mouse brain." (PMID 36007616, 2022). "Collectively, these results demonstrate that Abca7 deletion leads to sex-specific lipid dysregulation in the brain, providing insight into the underlying sex disparity in the aetiology of Alzheimer’s disease." (PMID 35620166, 2022). "To date, two large genome-wide association studies (GWAS) have implicated ABCA7 as a susceptibility locus for late-onset Alzheimer’s Disease." (PMID 36094096, 2022). "The adenosine triphosphate–binding cassette subfamily A member 7 gene (ABCA7) is associated with Alzheimer’s disease (AD) in large genome-wide association studies." (PMID 35361255, 2022). "Genetic variation in the ABCA7 gene is regarded as the fourth-highest risk factor for Alzheimer’s disease." (PMID 35620166, 2022). "SNPs in ABCA7 confer the largest genetic risk for Alzheimer’s Disease (AD) in African Americans (AA) after APOE ε4." (PMID 36421824, 2022). "The adenosine-triphosphate-(ATP)-binding cassette (ABC) transporter ABCA7 is a genetic risk factor for Alzheimer’s disease (AD)." (PMID 34976306, 2021). "Loss-of-function variants of ABCA7 increases the risk of susceptibility to Alzheimer's disease (AD) in Icelanders28." (PMID 33731780, 2021). "The ATP binding cassette subfamily A member 7 (ABCA7) gene is one of the significant susceptibility loci for Alzheimer’s disease (AD)." (PMID 33897360, 2021). "Genome-wide association studies (GWAS) originally identified ATP-binding cassette, sub-family A, member 7 (ABCA7), as a novel risk gene of Alzheimer’s disease (AD)." (PMID 30903345, 2019). "ABCA7 VNTR expansions result in a > 4-fold increased risk of Alzheimer’s disease, yet the technological challenges of investigating TR sequences have so far precluded further research and large-scale screening." (PMID 31727106, 2019).
Alzheimer disease (continued). "Although the association of ABCA7 risk variants with Alzheimer’s disease (AD) has been established worldwide, its effect size on the relative odds of being diagnosed with AD is significantly higher in African Americans." (PMID 31024289, 2019). "Mutations leading to premature termination codons in ATP-Binding Cassette Subfamily A Member 7 (ABCA7) are high penetrant risk factors of Alzheimer’s disease (AD)." (PMID 29589097, 2018). "In ABCA7, seven SNPs (including rs4147918) are cholesterol-related and showed a significant association with Late Onset Alzheimer's Disease, although little else is reported on the clinical effects caused by this polymorphism." (PMID 29064820, 2017). "ABCA7 has also been implicated recently in cancer progression;; the SNP itself has also been previously associated with Alzheimer's Disease." (PMID 29064820, 2017). "Premature termination codon (PTC) mutations in the ATP-Binding Cassette, Sub-Family A, Member 7 gene (ABCA7) have recently been identified as intermediate-to-high penetrant risk factor for late-onset Alzheimer’s disease (LOAD)." (PMID 28447221, 2017). "ATP-binding cassette transporter A7 (ABCA7) is expressed in the brain and linked with Alzheimer's disease." (PMID 26792809, 2016). "Several lines of evidence implicate a role for ABCA7 in the regulation of Alzheimer's disease (AD) risk and amyloid pathology." (PMID 26792809, 2016). "A recent study found that loss-of-function variants in ABCA7 (ATP-binding cassette transporter A7) confer greater risk for Alzheimer’s disease (AD)." (PMID 26654793, 2015). "A recent study found a significant increase of ABCA7 loss-of-function variants in Alzheimer’s disease (AD) cases compared to controls." (PMID 26654793, 2015). "In Alzheimer’s disease (AD), common variants in ABCA7 have been linked to AD and a recent meta-analysis provided compelling evidence that the SNP rs3764650 represents a new AD susceptibility locus." (PMID 23029339, 2012). "In addition, ABCA7 also has the activity of transporting cellular phospholipids to the extracellular apoA-I, and polymorphisms in the ABCA7 gene are associated with risk of Alzheimer’s disease." (PMID 40619002, 2025). "Genetic variations in ABCA7 have been found to be strongly linked to Alzheimer's disease." (PMID 39978466, 2025). "ABCA7 loss-of-function variants are associated with increased risk of Alzheimer’s disease (AD)." (PMID 38135757, 2024). "ABCA1, ABCA2 and ABCA7 have been linked to Alzheimer’s disease (AD)." (PMID 36385764, 2022). "Here, we show that Abca7 deletion leads to sex-specific lipid dysregulation in the brain, providing insight into the pathomechanism underlying the sex differences in the aetiology of Alzheimer’s disease." (PMID 35620166, 2022). "ABCA7 is one of the strongest susceptibility genes for Alzheimer’s disease." (PMID 35620166, 2022). "Despite the importance of lipid dysregulation in Alzheimer’s disease pathogenesis and the fact that ABCA7 is a lipid transporter and is strongly associated with Alzheimer’s disease, the role of ABCA7 in the regulation of brain lipids is largely unknown." (PMID 35620166, 2022). "Taken together, these studies identify a role of ABCA7 in brain SM metabolism and the importance of SM in synaptic plasticity and cognition, as well as provide a possible explanation for the association between ABCA7 and late-onset Alzheimer’s disease." (PMID 36007616, 2022). "Genetic studies including genome-wide studies have also associated inflammation-related genes to the etiology of Alzheimer’s disease (i.e. ABCA7, CLU, CR1, HLA-DRB1, HLA-DRB5, PICALM, and TREM2), further supporting the concept of neuroinflammation as a pathogenic factor in Alzheimer’s disease." (PMID 34335238, 2021).
Alzheimer disease (continued). "The genes represented by the age‐DMRs included a few notable members such as Cyp46a1 and Abca7, which are involved in cholesterol metabolism and implicated in Alzheimer's disease, and few members of the WNT signaling and mesenchyme developmental pathways (e.g., Fzd1, Fzd8, Wnt5a, Jak3, Ptk7, Nrp2)." (PMID 32790008, 2020). "We show that long-read sequencing with a single Oxford Nanopore Technologies PromethION flow cell per individual achieves 30× human genome coverage and enables accurate assessment of tandem repeats including the 10,000-bp Alzheimer’s disease-associated ABCA7 VNTR." (PMID 31727106, 2019). "While ABCA7 is expressed in a variety of tissues/organs, including the brain, recent genome-wide association studies (GWAS) have identified ABCA7 gene variants as susceptibility loci for late-onset Alzheimer’s disease (AD)." (PMID 29401741, 2018). "Recent genome-wide association studies (GWAS) have identified ABCA7 single nucleotide polymorphisms (SNPs) that increase Alzheimer's disease (AD) risk, however, the mechanisms by which ABCA7 may control AD risk remain to be fully elucidated." (PMID 26792809, 2016). "ABCA7 contributes to Alzheimer’s disease pathogenesis by modulating amyloid deposition and promoting microglial-mediated clearance of pathological aggregates." (PMID 40863490, 2025). "The relationship between the ABCA7 gene and Alzheimer’s disease (AD) has been widely studied across various populations." (PMID 39484364, 2024). "We uncovered a significant enrichment for processes regulating amyloid-beta formation, revealing that hc-RAE expression impacts Alzheimer’s disease risk genes that include APOE, ABCA7, CLU, NTRK2, and more." (PMID 36640362, 2023). "This association was modified by allelic variants in genes ABCA7, CLU, BDNF and MS4A6A that have been previously linked to Alzheimer’s disease." (PMID 37658429, 2023). "Differences in gene-wide DNA methylation of the Alzheimer’s disease (AD)-associated genes BIN1, HLA-DRB5, SORL1, SLC24A4, and ABCA7 are reported to be associated with AD in post-mortem brain samples." (PMID 36573011, 2023). "Since ABCA7 gene has been associated with late-onset Alzheimer’s disease (LOAD), we addressed the role of ABCA7 in the brain." (PMID 36007616, 2022). "ABCA1/ABCA7 is bound up with Alzheimer’s disease, ABCA4 is in connection with Stargardt macular degeneration, and ABCC8/SUR1 and ABCC9/SUR2 are both associated with diabetes." (PMID 35783291, 2022). "The top hits of the analyses of multi-omics Alzheimer’s disease datasets include genes ABCA7 and ATP1B1." (PMID 36094096, 2022). "Another recent study performed in the frame of the Alzheimer’s Disease Neuroimaging Initiative (ADNI) suggests also that ABCA7 acts very early in amyloid deposition." (PMID 33925691, 2021). "Several studies, including genome wide association studies (GWAS), have strongly suggested a central role for the ATP-binding cassette transporter subfamily A member 7 (ABCA7) in Alzheimer’s disease (AD)." (PMID 33925691, 2021). "The role of ABCA7 in Alzheimer's disease (AD) was discovered less than ten years ago when meta-analyses provided evidence that rs3764650 is a new AD susceptibility locus." (PMID 32098344, 2020). "We focused our analyses on an ABCA7 VNTR, for which we recently discovered that expanded alleles are a strong risk factor for Alzheimer’s disease." (PMID 31727106, 2019). "On the other hand, some ABC transporter family genes such as ABCA1, ABCA2, ABCA7 and ABCA12 are associated with Alzheimer's disease." (PMID 23281790, 2012). "Study of miRNA involvement in Alzheimer’s disease pathogenesis is relevant, since the associations of protein-coding genes (APOE4, ABCA7, BIN1, CLU, CR1, PICALM, TREM2) with the disease revealed as a result of GWAS make it difficult to explain its complex pathogenesis." (PMID 38680184, 2024).
Alzheimer disease (continued). "We additionally reviewed other risk genes associated with Alzheimer’s disease (ABCA7, SORL1 and TREM2), and no relevant variants were identified." (PMID 38287166, 2024). "Recent studies suggest that the ABC transporter ABCA7 may play a role in the development of brain disorders such as schizophrenia and Alzheimer’s disease." (PMID 23029339, 2012). "With the Alzheimer’s Disease Neuroimaging Initiative (ADNI) database, previous studies have investigated the correlation between 15 ABCA7 and 83 CR1 SNPs and CSF biomarkers." (PMID 34958020, 2022). "Lipoprotein clearance may play an important role in Alzheimer’s disease pathogenesis through the association of APOE and several other genes that function in lipid or lipoprotein metabolism, including Clusterin (CLU) and ATP binding cassette (ABC) transporter A7 (ABCA7,)." (PMID 32299494, 2020). "Both ABCA7 and ATP1B1 are candidate biomarkers of the Alzheimer’s disease." (PMID 36094096, 2022). "For example, several genes causing ALS and/or frontotemporal dementia (C9orf72, VCP, SQSTM1, OPTN, UBQLN2, GRN, CHMP2B) affect the autophagic machinery; and some Alzheimer’s Disease genes (APOE, TREM2, CD33, ABCA7) are preferentially or exclusively expressed in microglia." (PMID 33892821, 2021). "This method will enable researchers to carry out genetic polymorphism studies for genetic risk factors associated with late-onset Alzheimer’s disease (BIN1, CLU, ABCA7, CR1 and PICALM) without the use of expensive instrumentation and reagents." (PMID 23419238, 2013). "On the other hand, in Alzheimer’s disease, for example, changes have been identified in the methylation status of proteins such as human clusterin CLU; ATP binding cassette subfamily A member 7 ABCA7; MS4A6A; and CD2AP, which have been reported to contribute to the development of the disease." (PMID 39063168, 2024).